EGFR (epidermal growth factor receptor)
Diseases named in the same sentence as EGFR in open-access papers (continued):
Sharing a sentence is not in itself a finding about the gene and the disease.
lung cancer (continued). "Ligand is an important inducer of angiogenesis as well as EGFR-TKI resistance in EGFR mutation-positive lung cancer." (PMID 36910653, 2023). "Lung cancer is characterised by genetic modifications such as mutations inthe epidermal growth factor receptor (EGFR), fusion or rearrangement of the anaplastic lymphoma kinase (ALK), and various other abnormalities." (PMID 37928493, 2023). "Others were able to identify specific mutations of cfDNA in 1994, but it wasn’t until 2016 that the FDA approved the first liquid biopsy test for detecting EGFR gene mutations in lung cancer." (PMID 36900221, 2023). "In older patients with EGFR mutation-positive lung cancer who received EGFR-TKIs, the incidence of drug-induced ILD was significantly increased during osimertinib treatment compared with treatment with other EGFR-TKIs." (PMID 37179737, 2023). "On the view of these results, osimertinib was approved as a second-line treatment for advanced lung cancer with the EGFR T790M mutation." (PMID 36900362, 2023). "One example is the case of EGFR‐mutated lung cancer cells, which show reduced responsiveness to EGFR‐tyrosine kinase inhibitor (TKI) due to the presence of a ligand/receptor autocrine loop." (PMID 38077251, 2023). "As a result of its value as a diagnostic and therapeutic tool, EGFR plays a significant role in the management of lung cancer." (PMID 37754880, 2023). "The predictive Ceograph was trained to predict the benefitting score for each input cell spatial graph in the Lung Cancer Mutation Consortium 1 (LCMC1) dataset where all patients with EGFR mutation were treated with EGFR TKI Ttx." (PMID 37461694, 2023). "We constructed a CCCN and CFN from measurements of phosphorylation, acetylation, and ubiquitination in 10 different lung cancer cell lines with driver mutations in EGFR, ALK, ERBB2/HER2, ROS1, and DDR2, treated with four different TKIs." (PMID 36996232, 2023). "Our data highlight the ongoing need for improved access to therapeutic agents and clinical trials for lung cancer patients with EGFR/HER2 exon 20 mutations." (PMID 37622996, 2023). "Other studies have shown that lung cancer patients with EGFR mutation combined with CDKN2A deletion mutation have poor response to EGFR-TKI drugs." (PMID 36937524, 2023). "In this paper, we describe a pilot, longitudinal study with 20 patients with confirmed EGFR mutations in tissue biopsy for lung cancer." (PMID 37476385, 2023). "HCMV, EBV, and high-risk HPV infections are more frequent in EGFR-mutated lung adenocarcinomas, which indicates a possible viral impact on the etiology of this lung cancer subtype." (PMID 37131310, 2023). "So far, our understanding of the recognized resistance mechanisms against osimertinib, such as secondary resistance mutations like EGFR C797S, or the activation of alternative signaling pathways, is largely from studies in lung cancer." (PMID 37669963, 2023). "Non-small cell lung cancer (NSCLC), a sub-type of lung cancer, is frequently associated with activating mutations in receptor tyrosine kinases, including EGFR, MET, ALK, and ROS1, which disrupt tyrosine kinase signaling and drive cancer progression." (PMID 36996232, 2023). "EGFR mutations are not only an “early event” occurring during the initiation of lung cancer, they are the molecular driver of NSCLC." (PMID 36875137, 2023). "Gefitinib was the first molecularly targeted EGFR inhibitor that showed remarkable efficacy in lung cancer patients with EGFR mutations." (PMID 36902723, 2023). "The current study demonstrated the predictive ability of Th7R for recurrence in both EGFR wild-type and EGFR mutation-positive lung cancer." (PMID 37476074, 2023). "Mutations and increased expression of EGFR are common in various cancers, among which lung cancer is the most common." (PMID 37670265, 2023).
lung cancer (continued). "The new model differs from the previous model such that age was not an independent prognostic factor, which is consistent with the results of a study conducted on Chinese patients with BM from EGFR-mutated lung cancer." (PMID 37020869, 2023). "Patients with EGFR-mutated lung cancer treated at two major comprehensive cancer centers were retrospectively analyzed by the Kaplan–Meier method and log rank test." (PMID 37198447, 2023). "Lung cancer patients with co-mutations of EGFR and several other genes have a poor response to EGFR-TKIs." (PMID 36918558, 2023). "Another study reported the activation of EGFR-dependent Notch3 signalling after erlotinib treatment of lung cancer cell lines with EGFR mutations, which is responsible for the enrichment of stem cell-like cancer cells." (PMID 37441599, 2023). "EGFR tyrosine kinase inhibitor (TKI) therapy in EGFR-mutated lung cancer is limited by acquired resistance." (PMID 37198447, 2023). "The epidermal growth factor receptor (EGFR) mutation is a risk factor associated with brain metastases (BMs) in patients with non‐small cell lung cancer (NSCLC)." (PMID 37691552, 2023). "Excessive activation of EGFR is associated with the occurrence and development of various epithelial cell cancers such as lung cancer and colon cancer." (PMID 36674593, 2023). "Seemingly consistent with this finding, chromothripsis is frequently detected in lung cancers driven by EGFR mutations, and mutation of EGFR and ERBB2 is associated with more rearrangement events in LUADs." (PMID 36761982, 2023). "For lung cancer patients who are tested positive for activating EGFR mutations, tyrosine kinase inhibitors (TKIs) are now used as first-line treatment." (PMID 37542131, 2023). "A phase 1 study showed that pulse/continuous-dose erlotinib (1200 mg on days 1–2 and 50 mg on days 3–7 weekly) produced a 75% CNS response rate in EGFR mutated lung cancer patients with untreated brain metastases." (PMID 37118803, 2023). "This study describes the pooled experience from six academic medical centers evaluating efficacy of osimertinib among a real-world population of patients with lung cancers harboring atypical EGFR-activating mutations." (PMID 36879929, 2023). "In lung cancer, mutations in the epidermal growth factor receptor (EGFR) and anaplastic lymphoma kinase (ALK) gene rearrangements have emerged as significant targets." (PMID 37686423, 2023). "For example, the discovery of EGFR mutations in lung cancer led to the development of targeted therapies such as gefitinib and erlotinib, which have demonstrated improved outcomes compared to traditional chemotherapy." (PMID 37550388, 2023). "In this way, we decided to employ mathematical modeling to predict tumor evolution and direct reasonable treatment schedules for lung cancer patients harboring EGFR mutations." (PMID 37841421, 2023). "Analysis of a 1122 EGFR-mutant patient cohort revealed that multiple co-occurring oncogenic events are present in most advanced-stage EGFR-mutant lung cancers, including PIK3CA mutation." (PMID 37553597, 2023). "Specifically, upregulated complement factors were also found in the MPE, and C5 was associated with poor overall survival in the lung cancer patients with epidermal growth factor receptor mutation." (PMID 37649596, 2023). "In this context, the anti-HER3 antibody patritumab is able to overcome TKI resistance mediated by neuregulin, the HER3 ligand, in EGFR-mutated lung cancer models." (PMID 37894376, 2023). "PIK3CA mutations or gains are present in a subset of NSCLC with EGFR mutation and are associated with malignant biological behavior and EGFR-TKIs resistance in lung cancer." (PMID 37553597, 2023). "Precision therapy with oncogene-targeted drugs has dramatically changed the outcomes for lung cancer patients with tumors positive for mutated EGFR or fusion kinases including ALK and ROS1 and others." (PMID 36845684, 2023).
lung cancer (continued). "Systemic therapy targeted at epidermal growth factor receptor (EGFR) mutations for advanced-stage lung cancer, seems to produce satisfactory results in disease-free survival outcomes for patients with EGFR mutations." (PMID 37444585, 2023). "The epidermal growth factor receptor (EGFR) is a transmembrane glycoprotein of the ErbB family of tyrosine kinase receptors, and activated mutations of EGFR are a remarkable feature of lung cancer." (PMID 37189139, 2023). "Epidermal growth factor receptor (EGFR)‐mutated non‐small cell lung cancer (NSCLC) develops resistance to tyrosine kinase inhibitors (TKIs)." (PMID 35666038, 2023). "More research is needed to analyse the relationship between KRAS and EGFR gene mutations in the occurrence of lung cancer." (PMID 37340599, 2023). "In EGFR-mutated lung cancer, higher adjusted variant allele frequency (aVAF) has been associated with better efficacy of EGFR-TKI." (PMID 37954850, 2023). "Osimertinib, a highly potent small molecule inhibitor of epidermal growth factor receptor (EGFR), was used in the presence of an EGFR mutation as had been used previously in the successful treatment of lung cancer." (PMID 35953681, 2023). "This notion is particularly relevant to lung cancer, where the detection of circulating miRNAs showed that the levels of several miRNAs, such as miR-122 and miR-21, are predictors of EGFR mutation status and efficiency of TKI in patients with NSCLC28–32." (PMID 38057448, 2023). "Targets chemotherapy remains to play a leading role in the treatment for the majority of patients with advanced-stage LUAD, and EGFR-TKI is the first line drug for lung cancer patients harboring an EGFR mutation in routine clinical practice." (PMID 37065830, 2023). "Further studies should explore the specific ecosystem characteristics of the pleura in lung cancer patients with EGFR mutation by comparing the pleural metastatic niche between those with wild type and mutated EGFR." (PMID 37649596, 2023). "Since 2015, there have been many PDX models of lung cancer tested, and their therapeutic response to EGFR actionable mutation inhibitors is consistent with that observed in corresponding patients." (PMID 36911198, 2023). "Two studies examined the association of epidermal growth factor receptor (EGFR) mutations in lung cancer patients." (PMID 37686484, 2023). "One of the most frequently targeted genes in lung cancer is EGFR, which is mutated in approximately 10% of lung cancer patients." (PMID 37958784, 2023). "First, we found that GRP78 knockdown consistently suppresses EGFR protein expression level in a wide variety of human lung cancer cell lines harboring different EGFR mutational and amplification status." (PMID 37487081, 2023). "In human lung cancer cell line PC9 with Glu746-Ala750 deletion mutation in exon 19 of EGFR, gefitinib inhibited phosphorylated Akt (p-Akt) and phosphorylated mTOR (p-mTOR) expression." (PMID 38201251, 2023). "Those with early lung adenocarcinoma have the same rate of EGFR gene mutation as those with advanced lung cancer." (PMID 37390230, 2023). "After acquired resistance to EGFR-TKIs, EGFR-mutated lung cancer cells showed increased sensitivity to ferroptosis inducers." (PMID 37051544, 2023). "Overexpression or hyperactivation of EGFR is strongly associated with poor prognosis in a wide range of cancers, including lung cancer which is a leading cause of cancer mortality worldwide with limited therapeutic options." (PMID 37487081, 2023). "According to previous studies, ALK-rearranged lung cancer patients have similar or worse survival outcomes than EGFR-mutated patients." (PMID 37409244, 2023).
lung cancer (continued). "Exosomes released from lung cancer cells treated with Osimertinib can transfer wildtype EGFR to recipient EGFR-mutated cells, increasing their Osimertinib resistance." (PMID 37895415, 2023). "PD-L1 expression is correlated with TKIs response and prognosis in lung cancer patients with EGFR mutations." (PMID 36874015, 2023). "Approximately, 4%–12% of non‐small cell lung cancer (NSCLC) cases with mutations in the epidermal growth factor receptor gene (EGFR) harbor exon 20 insertion mutations (Exon 20ins)." (PMID 36583557, 2023). "Previous research indicates that EGFR mutations are not only an “early event” occurring during the initiation of lung cancer, but they are also the molecular driver of NSCLC." (PMID 36875137, 2023). "In similarity to HER2, HER3 expression is detected in a large fraction of NSCLC, and in EGFR-mutated lung cancers the levels are higher when compared to EGFR-wild type lung cancers." (PMID 37894376, 2023). "The EGFR is mutated in several lung cancer patients, and these patients can be treated with tyrosine kinase inhibitors." (PMID 37508387, 2023). "Further, a dynamic increase in plasma-derived EV KRAS or EGFR mutations seemed to be reliably suggestive of disease progression in pancreatic and lung cancer, respectively." (PMID 37542343, 2023). "Long‐term exposure to PM 2.5 also upregulated the expression of activated EGFR (pEGFR) in lung cancer cells harboring EGFR mutations (H1975)." (PMID 36975376, 2023). "Simultaneous occurrence of two or more rare EGFR mutations are extremely rare in lung cancer, and the incidence of EGFR L833V/H835L rare gene compound mutations is very low, and there is little clinical data and evidence of relevant treatment methods." (PMID 37989343, 2023). "The third-generation EGFR TKI osimertinib has demonstrated a clear DFS benefit for early-stage lung cancer patients with EGFR mutations." (PMID 36168085, 2023). "Epidermal growth factor receptor (EGFR) exon 20 insertion mutations (ex20ins) account for ≤ 12% of all EGFR‐mutant nonsmall cell lung cancers." (PMID 36269676, 2023). "The mutation in the gatekeeper residue of EGFR, T790M, is the most common mechanism of acquired resistance to EGFR inhibitors in EGFR mutant lung cancer." (PMID 38017514, 2023). "EGFR mutations found in lung cancer usually affect the intracellular kinase domain, while EGFR mutations of GBMs affect the extracellular domain and are found in the context of EGFR amplification." (PMID 37537946, 2023). "Randomised clinical trials of lung cancer patients with EGFR-sensitive mutation showed that first-line treatment with EGFR-TKIs achieved similar PFS benefits to chemotherapy in smokers and never-smokers." (PMID 37007097, 2023). "The EGFR is an oncogene in lung cancer that is frequently mutated increasing protein kinase activity." (PMID 37508387, 2023). "Mutated EGFR is a major driver in lung cancer and studies showed that cancer patients have an increased risk to develop severe COVID-19 and a threefold increased risk to die by a SARS-CoV-2 infection." (PMID 37402592, 2023). "Mutations in the epidermal growth factor receptor (EGFR) are a key oncogenic driver in nonsmall cell lung cancer (NSCLC)." (PMID 36269676, 2023). "Non‐small cell lung cancer (NSCLC) patients harboring epidermal growth factor receptor (EGFR)‐mutated who progressed on EGFR tyrosine‐kinase inhibitor (EGFR‐TKI) therapy have limited therapeutic options." (PMID 37584242, 2023). "For example, MET activation, another cause of EGFR TKIs resistance in lung cancer, can promote drug resistance by reactivating PI3K/AKT and MEK/ERK signaling pathways in the presence of EGFR inhibition." (PMID 37638338, 2023). "Patients with epidermal growth factor receptor (EGFR)‐mutated, advanced non–small cell lung cancer have received immunochemotherapy as one of the treatment options after tyrosine kinase inhibitor (TKI) failure." (PMID 36866788, 2023).
lung cancer (continued). "Although lung cancer is the leading cause of death in human cancer, the cancer with the highest EGFR mutation frequency is glioblastoma (~27%), which is approximately 12% higher than lung carcinoma (~15%)." (PMID 37333807, 2023). "The FGF7-FGFR2 over-expressing lung cancer-associated fibrosis (CAF) type robustly protects EGFR-mutated cancer cells to maintain osimertinib resistance." (PMID 36717865, 2023). "Inherent and acquired resistance in EGFR-mutated lung adenocarcinomas constitutes a significant obstacle to improving lung cancer treatment outcomes." (PMID 36902280, 2023). "Osimertinib is the standard first‐line therapy for patients diagnosed with advanced stage non‐small cell lung cancer (NSCLC) that is positive for EGFR mutations." (PMID 36578073, 2023). "Remarkably, in some non‐small cell lung cancer cases, new undiscovered EGFR mutations or translocations were identified, and new treatment recommendations were provided in 40% of cases." (PMID 36251535, 2023). "In lung cancer, the association between aberrant methylation profiles and resistance to anti-EGFR therapy is still understudied." (PMID 37152062, 2023). "For example, in lung cancer, ctDNA enables the detection of mutations that are potential therapeutic targets, such as epidermal growth factor receptor (EGFR) mutations." (PMID 37371673, 2023). "What are the efficacy and safety of gefitinib plus chemotherapy in patients with untreated epidermal growth factor receptor (EGFR) mutated non–small cell lung cancer (NSCLC) brain metastases?" (PMID 36753281, 2023). "The result of lung cancer gene detection using paraffin section showed L858R mutation in exon 21 of the EGFR gene along with G12A/V/R/C and G13C mutations in exon 2 of the KRAS gene." (PMID 36890493, 2023). "Recent studies on lung cancer have described an association between EGFR mutation and an increased incidence of DVT, PE, and other thromboembolic complications." (PMID 37232831, 2023). "PIK3CA and ErbB2 gene co-variation most associated with primary EGFR-TKIs resistance in EGFR-mutant lung cancer patients." (PMID 37553597, 2023). "Epidermal growth factor receptor (EGFR) mutations are major oncogenic alterations in non‐small cell lung cancer (NSCLC), particularly adenocarcinoma, and have been identified as molecular targets." (PMID 37605832, 2023). "Even in EGFR-mutation-driven lung adenocarcinoma (LUAD), dysregulated EGFR further accelerates the occurrence and progression of lung cancer." (PMID 37240137, 2023). "Glioblastoma and lung cancer mutations that are resistant to antibody-mediated EGFR inhibition and mutations were observed in colorectal malignancies." (PMID 36768973, 2023). "In lung cancer cells, EGFR mutations are associated with anti-apoptotic signaling (e.g., through AKT and STAT), which promotes survival." (PMID 37927598, 2023). "In older patients with EGFR mutation-positive lung cancer, the incidence of drug-induced ILD was significantly increased during osimertinib treatment." (PMID 37179737, 2023). "In lung cancer cells with EGFR mutations, the combinatorial treatment modality of SCD1 and EGFR-tyrosine kinase inhibitors (TKIs) showed better antitumor effects." (PMID 37047797, 2023). "Another study showed that lung cancer patients with the L858R EGFR mutation had more inflammatory tumors with higher CD4 and CD8+ T cell expressions compared to those with the exon 19 deletion mutation." (PMID 37033978, 2023). "Molecular targeted drugs known as epidermal growth factor receptor tyrosine Kinase Inhibitors (EGFR-TKIs) are regarded as standard first-line therapies for advanced EGFR-mutated lung adenocarcinoma contributing to the reduction of lung cancer mortality." (PMID 37697337, 2023). "In EGFR-mutated lung cancer cells, SOX2 overexpression promotes resistance to erlotinib by repressing the expression of proapoptotic proteins BIM and BMF." (PMID 38096163, 2023).